CXCR4 (C-X-C motif chemokine receptor 4)
Diseases named in the same sentence as CXCR4 in open-access papers (continued):
Sharing a sentence is not in itself a finding about the gene and the disease.
pulmonary fibrosis (continued). "Furthermore, in a murine bleomycin model of pulmonary fibrosis, AD-114 reduced the accumulation of fibrocytes (CXCR4+/Col1+/CD45+) in fibrotic murine lungs and ameliorated the degree of lung injury." (PMID 29453386, 2018). "Indeed, while some investigators have suggested that SDF-1 and its receptor, CXCR4, augment pulmonary fibrosis; other reports suggest a crucial role of SDF-1 in neo-alveolarization." (PMID 28701189, 2017). "The CXCR4/ CXCL12 axis contributes to pulmonary fibrosis development." (PMID 28968441, 2017). "Several studies using CXCR4 antagonists have reported attenuated BLM-induced lung fibrosis in mice." (PMID 26998906, 2016). "In addition, inhibition of CXCR4/CXCL12 had been shown to reduce lung fibrosis in a BLM induced murine model of PF." (PMID 26998906, 2016). "Fibrocytes also express several chemokine receptors, particularly CXCR4, which has been shown to mediate the effect of stromal derived factor-1 (SDF-1/CXCL12), a specific ligand for CXCR4, in causing migration of fibrocytes in pulmonary fibrosis." (PMID 27309347, 2016). "Prompted by these previous data, we demonstrated that TMP might inhibit corneal neovascularization, attenuate pulmonary fibrosis, and improve microcirculation by down-regulating CXCR4 expression both in vivo and in vitro." (PMID 26275042, 2015). "The SDF-1/CXCR4 axis plays a critical role in the pathogenesis of pulmonary fibrosis." (PMID 24505417, 2014). "Moreover, TMP treatment significantly attenuates bleomycin-induced rat pulmonary fibrosis, while immunofluorescence shows a notably decreased amount of CXCR4-positive cells in the TMP-treated group." (PMID 24505417, 2014). "In addition, we demonstrated that MSX-122 blocks bleomycin-induced lung fibrosis involving chemotaxis and homing of CXCR4-positive mesenchymal progenitor cells into the lungs, the same critical mechanisms involved in cancer metastasis." (PMID 22485156, 2012). "The combined observations suggest that CSD peptide treatment provides protection against bleomycin-induced lung fibrosis in large part by inhibiting the expression of CXCR4 by monocytes and fibrocytes and thereby inhibiting their migration into damaged lung tissue." (PMID 21722364, 2011). "Targeting CXCR4 as a therapeutic strategy in humans is appealing because this approach has been effective in several murine models of pulmonary fibrosis, albeit with the usual caveats regarding the dissimilarities between mouse models and human pulmonary fibrosis." (PMID 36853800, 2023). "We previously reported that human fibrocyte CXCR4 expression is regulated by the mTOR pathway in vitro and that sirolimus inhibits CXCR4 expression and fibrocyte traffic both in vitro and in experimental animals and attenuates bleomycin-induced pulmonary fibrosis." (PMID 36853800, 2023). "Indeed, we showed treatment with CXCR4 antibody attenuates BLM-induced pulmonary fibrosis." (PMID 34082837, 2021). "Based on our findings, we propose that decreased levels of IGFBP‐4 in SSc fibroblasts may be responsible for increased CXCR4 in lung fibrosis and ultimately the promotion of CXCR4‐dependent chemotaxis of circulating monocytes and inflammatory cells, contributing to pulmonary fibrosis." (PMID 31482149, 2019). "Indeed, various studies have shown that inhibition of CXCR4 results in anti-fibrotic effects in vitro and ameliorated bleomycin induced lung fibrosis in vivo, suggesting that this chemokine receptor might be a therapeutic target in fibrotic lung diseases." (PMID 29453386, 2018). "We found that AMD3100 inhibited MMP19-induced monocyte adhesion to HPMECs and CXCR4+ monocyte accumulation in lung tissues, and alleviated MMP19-induced exacerbation of BLM-induced pulmonary fibrosis." (PMID 36915092, 2023). "MMP19 promoted E(nd)MT by interacting with ET1 and stimulated monocyte infiltration into lung tissues via the SDF1/CXCR4 axis, thus aggravating BLM-induced pulmonary fibrosis." (PMID 36915092, 2023).
pulmonary fibrosis (continued). "Notably, CD4+ T cells in cluster T9 expressed high levels of KLF6 that positively regulates the expression of TGFβ and molecules in the TGFβ pathway, AREG (amphiregulin) that is involved in pulmonary fibrosis, and CXCR4 that may promote T-cell migration to the lung." (PMID 35558069, 2022). "Our identification within IPF tissue of high expression of CXCR4 in the immune infiltrate ROIs and the expression of CXCL12 within fibroblastic foci suggests a potentially similar immune exclusion mechanism in lung fibrosis." (PMID 35977489, 2022). "We demonstrated the pulmonary expression of SDF1 and CXCR7 was earlier than that of the CXCR4 expression, and that result suggested that CXCR7 is an early factor in the development of pulmonary fibrosis." (PMID 34082837, 2021). "The results of these experiments showed that VEGFR1-TK signaling induces pulmonary fibrosis by promoting the migration of VEGFR1+ cells, which is dependent on the SDF-1/CXCR4 axis." (PMID 34082837, 2021). "Some researchers have used MSCs genetically modified with factors such as CXCR4, basic fibrosis growth factor (bFGF), and HGF to mitigate the effects of acute and chronic lung injuries and pulmonary fibrosis." (PMID 33747095, 2021). "In present study, we concluded that G-CSF exerted antifibrotic effects in bleomycin-induced lung fibrosis, in part by promoting BMSCs homing to injured lung tissues via SDF-1/CXCR4 chemotaxis." (PMID 32601321, 2020). "In conclusion, G-CSF exerted antifibrotic effects in bleomycin-induced lung fibrosis, in part by promoting BMSC homing to injured lung tissues via SDF-1/CXCR4 chemotaxis." (PMID 32601321, 2020). "These cells have been shown to be recruited to mouse lungs in models of bleomycin-induced pulmonary fibrosis through CXCL12/SDF-1, which interacts with CXCR-4." (PMID 30764496, 2019). "Since CD45+/COL1+/CXCR4+ fibrocytes were expanded in the bone marrow and have been reported to contribute to bleomycin-induced pulmonary fibrosis, we next stained the PBMC-differentiated cells with antibodies specific for CD45, Collagen I, and CXCR4." (PMID 31750010, 2019). "Involvement of the CXCR4/SDF-1 axis is discussed in several diseases including inflammatory bowel diseases, ischemia/reperfusion injury, and in idiopathic pulmonary fibrosis." (PMID 29566745, 2018). "The results of many studies have indicated that the SDF-1/CXCR4 axis is closely related to pulmonary diseases, such as PAH, pulmonary fibrosis, and acute lung injury." (PMID 28774332, 2017). "Specifically, inhibition of CXCR4/CXCL12 signaling with anti-CXCL12 antibody reduced recruitment of CD45+ ColI+ CXCR4+ fibrocytes in BLM exposed mice and reduced lung fibrosis." (PMID 26998906, 2016). "The approved, i.v.-administered CXCR4 antagonist, plerixafor (AMD3100), had been evaluated in a number of BLM-induced pulmonary fibrosis models including one recently-retracted article." (PMID 26998906, 2016). "The CXCR4 antagonist, AMD3100, decreased CXCR4 expression and significantly attenuated pulmonary fibrosis in rats." (PMID 24505417, 2014). "The SDF-1/CXCR4 axis is involved in the pathogenesis of several diseases, such as HIV, cancer, pathological angiogenesis and myocardial and pulmonary fibrosis." (PMID 24505417, 2014). "Therefore, we speculated that TMP might regulate CXCR4 expression in pulmonary fibrosis." (PMID 24505417, 2014). "Consistent with our findings of CXCR4 predominance on circulating fibrocytes in other mouse models of pulmonary fibrosis, the majority of fibrocytes in NY1DD mice express CXCR4." (PMID 22442712, 2012). "Previously, we had studied the role of the CXCL12/CXCR4-axis in a rodent model of bleomycin-induced lung injury and reported that TN14003 blocked bleomycin-induced lung fibrosis." (PMID 22485156, 2012). "Fibrocytes were found to express CXCR4 and to migrate in response to CXCL12 in vitro and in vivo in a model of bleomycin-induced pulmonary fibrosis." (PMID 21219601, 2011).
pulmonary fibrosis (continued). "The administration of the CXCR4 antagonist AMD3100 correspondingly diminishes B lymphocyte accumulation and neutrophil infiltration in the lungs, thereby directly mitigating the progression of pulmonary fibrosis." (PMID 41394824, 2025). "Previous studies have demonstrated that the activation of CXCL12/CXCR4 signaling pathway could contribute the neutrophil accumulation and retention in the lungs during ALI and accelerate lung fibrosis." (PMID 38352962, 2024). "Treatment of bleomycin-induced fibrotic rats with the CXCR4 antagonist, AMD3100, reduced CXCL12 levels in bronchoalveolar lavage (BAL) fluids, resulting in a reduction in pulmonary fibrocytes and an overall improvement in pulmonary fibrosis phenotypes." (PMID 36164329, 2022). "CXCR4 is the main chemokine receptor expressed on circulating fibroblasts in humans and mice, and there is a direct correlation between the lung and plasma levels of CXCL12 and the number of circulating pulmonary fibrocytes in patients with pulmonary fibrosis." (PMID 34001199, 2021). "The CXCR4 antagonist AMD070 alleviated hepatic and pulmonary fibrosis in mice." (PMID 33635004, 2021). "Moreover, in a murine model of bleomycin-induced pulmonary fibrosis, the fibrocytes (CD45+ Collagen I+ CXCR4+) infiltrated as early as two days after bleomycin exposure." (PMID 32268503, 2020). "In general, CXCL12 triggers CXCR4 to activate G protein-coupled signaling pathways including mitogen-activated protein kinase (MAPK), which subsequently induce several cellular responses including gene expression and pulmonary fibrosis." (PMID 29499695, 2018). "Neonatal rodents with experimental BPD have unchanged lung SDF-1 expression, while lung tissue of patients with idiopathic pulmonary fibrosis have an increased number of SDF-1 expressing cells and blockade of the SDF-1 receptor, CXCR4, decreases pulmonary fibrosis." (PMID 28701189, 2017). "Based on this evidence, the Ad-MSCs were predicted to promote pulmonary fibrosis after irradiation because the interaction between SDF-1 and CXCR4 was hypothesised to initiate the migration of ‘fibrocytes' from bone marrow to injured sites." (PMID 25736907, 2015). "Although the SDF-1/CXCR4 axis increased the number of engraftment of MSCs, we found that engraftment of MSCs did not ameliorate lung injury or pulmonary fibrosis." (PMID 24573542, 2014). "This study indicated that CXCR4+cells are the predominant population of fibrocytes recruited to fibrotic lungs of mice in a bleomycin model of lung fibrosis and that neutralizing CXCL12 significantly reduced lung fibrosis." (PMID 24478703, 2014). "In summary, the results obtained in the present study suggest that regulating the SDF-1/CXCR4 axis through TMP might inhibit corneal neovascularization, attenuate pulmonary fibrosis, and improve microcirculation." (PMID 24505417, 2014). "We found that AMD3100 significantly inhibited MMP19 induced monocyte adhesion to HPMECs and CXCR4+ monocyte accumulation in lung tissues, and alleviated the MMP19-induced increase in hydroxyproline levels and accumulation of ECM and collagen in BLM-induced pulmonary fibrosis." (PMID 36915092, 2023). "Therefore, the CXCL12/CXCR4 axis and CTGF play important roles in pulmonary fibrosis." (PMID 25121739, 2014). "Moreover, the concentration of CXCL12 in the plasma of patients with idiopathic pulmonary fibrosis was significantly higher than in healthy controls, suggesting that circulating fibrocytes are recruited through the CXCR4 - CXCL12 axis and contribute to lung fibrosis in this patient population." (PMID 21219601, 2011). "It is unknown how and to what extent CXCR4 signaling affects lung fibrosis and whether the lack of an inhibitory effect on CXCR4 is one of the reasons for the failure of compound 18a to attenuate lung fibrosis." (PMID 35562519, 2022). "Patients with dSSc and those with lung fibrosis revealed higher anti-CXCR3 and anti-CXCR4 ab levels compared with those with lSSc and without SSc-ILD." (PMID 29566745, 2018).
pulmonary fibrosis (continued). "Since HGF-expressing, CXCR4+ cells in UIP did neither co-stain with vimentin nor with α-SMA, we assume that these cells are not fibrocytes that were recently described to play a major role in the pathogenesis of pulmonary fibrosis." (PMID 23840329, 2013).
neuroblastoma (68 papers, 2005 to 2025). Neuroblastoma (NB) is the most common solid, extracranial childhood tumor. "We have identified further hypoxia-associated prognostic factors for neuroblastoma including CXCR4, PGK1 and AQP1 leading to increased metastases." (PMID 35328549, 2022). "CXCR4 expression is associated with a highly aggressive undifferentiated histopathologic type and poor prognosis in neuroblastoma tumours." (PMID 36140541, 2022). "It still needs to be determined if this hypoxia-associated mode of action is the leading mechanism in neuroblastoma, as CXCR4 is expressed in many different neuroblastoma cell lines under normoxic conditions, Kelly and SH-SY5Y cells amongst them." (PMID 33467498, 2021). "A factor that is well known to be associated with migration in neuroblastoma is the chemokine receptor CXCR4." (PMID 33467498, 2021). "CXCR4-overexpressing cells were also shown to be associated with increased incidence of bone marrow metastases in an in vivo neuroblastoma xenograft model." (PMID 26729169, 2015). "Both CXCL12 and CXCR4 expression have been associated with tumorigenesis in many cancers including breast, ovarian, renal, prostate, and neuroblastoma." (PMID 20376365, 2010). "Ten human neuroblastoma-derived cell lines from patients with high-risk disease were screened for surface expression of CXCR4 by flow cytometry." (PMID 20028517, 2009). "Of note, the MIF/CXCR4 signaling axis has been implicated in the survival, invasion, and drug resistance of patient-derived neuroblastoma cells in the bone marrow microenvironment and may provide an explanation for the high propensity of bone metastasis in neuroblastoma." (PMID 38732068, 2024). "Analysis of public gene expression datasets revealed that both MIF and CXCR4 were highly expressed in primary neuroblastoma tumors and BM-derived disseminated neuroblastoma tumor cells." (PMID 41159021, 2025). "The CXCR4 chemokine pathway was also well-validated in other forms of primary brain cancer such as medulloblastoma and neuroblastoma." (PMID 36980182, 2023). "The underlying cellular mechanism linking 3D growth with augmented CXCR4 expression in neuroblastoma cells is an open question." (PMID 36980635, 2023). "In neuroblastoma, the expression status of NF-κB-p65 was positively correlated with the expression level of CXCR4." (PMID 36290780, 2022). "CXCR4 favours neuroblastoma metastasis to the liver as well as the lungs and increased bone marrow invasion." (PMID 36140541, 2022). "Bradykinin and ATP leaking from inflammatory processes or damaged cells promoted the attraction of neuroblastoma cells to the bone marrow through stimulating chemokine CXCL12/CXCR4/CXCR7 interactions." (PMID 34831167, 2021). "It has been shown that high expression of CXCR4 in neuroblastoma correlates with a significantly impaired outcome compared to low CXCR4 expression." (PMID 33671521, 2021). "The chemokine receptor CXCR4 has been well established as a marker for metastatic homing in various solid tumors including neuroblastoma." (PMID 33467498, 2021). "It has been shown that a high expression of CXCR4 in neuroblastoma correlates with a significantly impaired outcome compared to a low CXCR4 expression." (PMID 33467498, 2021). "Several adverse factors have been linked to oncogenesis, tumor progression and metastases of neuroblastoma including NMYC amplification, the neural adhesion molecule NCAM, as well as CXCR4 as a promoter of metastases." (PMID 33467498, 2021). "In neuroblastoma, CXCR4 and CXCR7 expression are different or even opposed, as CXCR7 is observed in neural-associated compartment of differentiated and matured tumors while CXCR4 in highly aggressive and undifferentiated tumors." (PMID 33937018, 2021). "Expression of CXCR4 in neuroblastoma correlates with a significantly worse outcome compared with a low CXCR4 expression." (PMID 33467498, 2021).